RPS10P20 (ribosomal protein S10 pseudogene 20)
Synonyms: RPS10_11_1233
Gene: Transcribed processed pseudogene on chromosome 12 (48,487,946 to 48,488,408, forward strand). Ensembl gene ENSG00000240443.
Diseases named in the same sentence as RPS10P20 in open-access papers:
RPS10P20 is named in the same sentence as 1 disease in open-access papers, as found by Europe PMC text mining. Sharing a sentence is not in itself a finding about the gene and the disease. The quoted sentences say what the papers report.
breast carcinoma (2 papers, 2020 to 2021). "We find that increased CTSLP8 (Wald p-value = 5.0 × 10− 05), increased EEF1GP4 (Wald p-value = 1.0 × 10− 06), decreased HLA-K (Wald p-value = 8.0 × 10− 05), increased CBX1P3 (Wald p-value = 1.0 × 10− 03), and increased RPS10P20 (Wald p-value = 2.0 × 10− 03) indicate worse prognosis in breast cancer." (PMID 32241256, 2020).